BHLHE40 (basic helix-loop-helix family member e40)
Diseases named in the same sentence as BHLHE40 in open-access papers (continued):
Sharing a sentence is not in itself a finding about the gene and the disease.
gastric cancer (3 papers, 2020 to 2025). A primary or metastatic malignant neoplasm involving the stomach. "Thus, BHLHE40 appears to be significantly upregulated in gastric cancer and associated with tumor differentiation status." (PMID 32577154, 2020). "Further, we show that BHLHE40 selects its targets by cooperation with other transcription factors that regulate the expression, and the function, of BHLHE40, such as HIF1α in gastric cancer and in HCC." (PMID 32577154, 2020). "In gastric cancers, hypoxia induced BHLHE40 expression while the HIF-1α protein inhibitor decreased the expression of BHLHE40." (PMID 32577154, 2020). "Taken together, these studies indicate that in gastric cancer, an increase in BHLHE40 in tumor cells is indicative of hypoxia, which results in an increase of BHLHE40 expression driven by an increase in the HIF complex." (PMID 32577154, 2020). "Two studies showed that 83% gastric cancer tissues stained positive for BHLHE40 and expression increased during the tumor progression from well differentiated to poorly differentiated." (PMID 32577154, 2020). "Moreover, treatment with curcumin, which is known to protect from hypoxia, decreased HIF1α expression in gastric cancer cells, resulting in suppression of BHLHE40 expression." (PMID 32577154, 2020). "BHLHE40 was upregulated in gastric cancer compared with normal tissue." (PMID 32577154, 2020).
lung carcinoma (3 papers, 2015 to 2023). "The basic-helix-loop-helix (BHLH) protein BHLHE40, which is overexpressed in gastric, breast, and brain tumors; and downregulated in colorectal, esophageal, pancreatic, and lung cancer." (PMID 36895015, 2023). "Another study revealed that Th2 cells stimulate lung cancer metastasis by activating neutrophils through complement C3, and our findings also identified that BHLHE40 significantly correlated with Th1 and Th2 cell differentiation, Th17 cell differentiation and PD-1 checkpoint in GO and KEGG analyses." (PMID 37773521, 2023).
parasitemia (3 papers, 2023 to 2026). "Loss of Bhlhe40 expression in mice results in higher Il10 expression, higher peak parasitemia, and a delay in parasite clearance." (PMID 37843306, 2023). "Previous studies have reported a disturbed balance between proinflammatory IFN-γ and anti-inflammatory IL-10 in Bhlhe40-/- mice during intracellular parasite infections." (PMID 38271477, 2024). "Bhlhe40−/− mice exhibited a significant difference in parasite burden from peak parasitemia through clearance compared to WT mice." (PMID 37843306, 2023). "Mechanistically, BHLHE40 suppresses IL-10 production by co-binding to a regulatory region with c-Maf in the Il10 locus in T cells and myeloid cells, which in turn promotes proinflammatory cytokine production during intracellular parasite infections." (PMID 38271477, 2024).
viral infection (3 papers, 2017 to 2022). "Basic helix–loop–helix family member E40 (Bhlhe40) is an important transcription factor, which is involved in tumors, inflammation, apoptosis, viral infection, and hypoxia." (PMID 36304536, 2022). "Finally, BHLHE40 set a balance between pro-inflammatory and anti-inflammatory Th1 cell fate determination inducing INF-γ expression, an innate immune response to viral infections." (PMID 34603282, 2021).
atherosclerosis (2 papers, 2025). A disease characterized by the build-up of fatty material and calcium deposition in the arterial wall resulting in partial or complete occlusion of the arterial lumen. "Taken together, our findings demonstrate that the rs6190 SNP promotes hypercholesterolemia and atherosclerosis in vivo through upregulation of Pcsk9 and Bhlhe40 in liver." (PMID 40591411, 2025). "The SNP effect on atherosclerosis was blocked by in vivo liver knockdown of Pcsk9 and Bhlhe40." (PMID 40591411, 2025). "Finally, considering our hypothesis of Pcsk9 and Bhlhe40 as mechanistic mediators of the SNP effect, we tested the effect of in vivo knockdown of these genes on the SNP-mediated effect on cholesterol and atherosclerosis through AAV8 vectors." (PMID 40591411, 2025). "First, while we established the protective role of the Piezo1/BHLHE40/SLC7A11 axis in LPS-induced sepsis, its function in chronic vascular diseases such as atherosclerosis requires validation in respective animal models and clinical specimens." (PMID 41372156, 2025). "Although our study links mechanotransduction to vascular inflammation via the Piezo1/BHLHE40/SLC7A11 axis, validation in disease models such as atherosclerosis or other cardiovascular pathologies is lacking." (PMID 41372156, 2025).
cardiac hypertrophy (2 papers, 2013 to 2023). "Bhlhe41 was shown to modulate hypertension susceptibility, Per1 was found to play a role in regulating blood pressure, Dbp functions in cardiac hypertrophy, ventricular function, and contractility, while Bhlhe40 functions in cardiac morphogenesis and development." (PMID 24255707, 2013).
colitis (2 papers, 2022 to 2025). Inflammation of the colon. "Additionally, Bhlhe40-deficient CD4+ T cells fail to induce colitis in a T cell transfer colitis model, further supporting our finding that induction of BHLHE40 expression in pathologically relevant CD4+ T cells in the gut is pathogenic to colitis." (PMID 40906156, 2025).
colorectal tumors (2 papers, 2022 to 2023). "Both ETV1 and JMJD1A are reportedly overexpressed in colorectal tumors, providing one plausible explanation for BHLHE40 upregulation in this cancer." (PMID 36890812, 2023). "In agreement with this, analysis of published microarray data revealed that BHLHE40 mRNA levels are upregulated in colorectal tumors and may be a predictor of disease recurrence and disease-free survival." (PMID 36890812, 2023). "We demonstrate that the BHLHE40 gene is upregulated in colorectal tumors." (PMID 36890812, 2023). "Altogether, these data indicate that upregulation of BHLHE40 in human colorectal tumors may promote their growth and aggressiveness." (PMID 36890812, 2023). "Corroborating previous studies, we found that BHLHE40 is upregulated in colorectal tumors." (PMID 36890812, 2023). "A more recent report analyzed BHLHE40 protein levels in ten colorectal tumors by immunohistochemistry and claimed overexpression, but no quantification or statistical analysis was provided." (PMID 36890812, 2023). "Since ETV1, JMJD1A and JMJD2A are implicated in many different types of malignancies, BHLHE40 upregulation by these three proteins is likely not limited to colorectal tumors." (PMID 36890812, 2023).
esophageal squamous cell carcinoma (2 papers, 2020 to 2025). Esophageal squamous cell carcinoma (ESCC) is a type of esophageal carcinoma (EC) that can affect any part of the esophagus, but is usually located in the upper or middle third. "One such disease is esophageal squamous cell carcinoma (ESCC), where a study of 241 patients showed that BHLHE40 expression significantly increased in intraepithelial neoplasia (IEN) compared with normal precursor tissue." (PMID 32577154, 2020).
experimental autoimmune encephalomyelitis (2 papers, 2023 to 2025). An autoimmune demyelinating disease of the central nervous system that is produced experimentally in animals by the injection of homogenized brain or spinal cord in Freund's adjuvant. "We identified that Bhlhe40 in CCR6high MP CD4+ T cells as a key regulator of GM-CSF expression through IL-23 and IL-1β signaling, contributing to central nervous system (CNS) pathology in experimental autoimmune encephalomyelitis." (PMID 37121980, 2023).
gastritis (2 papers, 2021 to 2025). Inflammation of the stomach. "In addition, the high expression of BHLHE40 in gastric epithelial cells increased the production of CXCL12 by interacting with p-STAT3 in Helicobacter pylori-associated gastritis, which further aggravated the development of gastritis." (PMID 34917665, 2021).
glioblastoma (2 papers, 2020 to 2023). The most malignant astrocytic tumor (WHO grade IV). "In patients with recurrent glioblastoma, BHLHE40 expression also correlated negatively with apoptosis." (PMID 32577154, 2020). "In patients with recurrent glioblastoma, BHLHE40 expression correlated negatively with apoptosis." (PMID 32577154, 2020).
Hypertension (2 papers, 2013 to 2022). The presence of chronic increased pressure in the systemic arterial system. "Thus, we aim to investigate whether Bhlhe40 participated in hypertension/hypertrophic stimulus-induced atrial fibrosis, atrial inflammation, and the progression of AF and to confirm the underlying mechanism in Bhlhe40-knockdown mice." (PMID 36304536, 2022). "Interestingly, as we know, hypertension, LV hypertrophy, and congestive heart failure, induced by Ang II or pressure overload in mice models, predispose the mice to AF, suggesting that Bhlhe40 may be involved in the development of AF." (PMID 36304536, 2022).
pulmonary fibrosis (2 papers, 2022 to 2024). Chronic progressive interstitial lung disorder characterized by the replacement of the lung tissue by connective tissue, leading to progressive dyspnea, respiratory failure, or right heart failure. "Bhlhe40 deficiency attenuates pulmonary fibrosis and repressed the PI3K/AKT/GSK-3β/β-catenin-integrated signaling pathway in mice and in A549 cells." (PMID 36304536, 2022). "In addition, our previous study has reported that Bhlhe40 deficiency ameliorated pulmonary fibrosis and inflammation through the PI3K/AKT/GSK-3β/β-catenin integrated signaling pathway by using Bhlhe40 knockout (Bhlhe40−/−) mice." (PMID 38402153, 2024).
Sepsis (2 papers, 2025). Sepsis is defined as life-threatening organ dysfunction caused by a dysregulated host response to infection. "Bhlhe40 overexpression significantly attenuated the sepsis-induced elevation in plasma MDA, suggesting protection against oxidative stress and potential ferroptotic processes." (PMID 41372156, 2025). "Concomitantly, Bhlhe40 overexpression attenuated sepsis-induced pulmonary edema, as evidenced by reduced lung wet/dry weight ratios." (PMID 41372156, 2025). "Our results demonstrated that endothelial Bhlhe40 overexpression significantly ameliorated multiple pathological features of LPS-induced sepsis." (PMID 41372156, 2025). "In LPS-induced sepsis, mice with endothelial-specific BHLHE40 overexpression attenuated pulmonary vascular leakage, neutrophil infiltration, and systemic inflammation." (PMID 41372156, 2025).
thyroid cancer (2 papers, 2020 to 2024). "Aberrant signaling in thyroid cancer cells ensured that BHLHE40 cooperated with Notch signaling to promote target gene transcription and tumor aggression." (PMID 32577154, 2020). "To uncover the most distinct genes in different thyroid cancer subtypes, we screened BCL2, BHLHE40, MICAL2, TGM2, and TPO by comparing each pair of existing subtypes." (PMID 39872516, 2024). "Not surprisingly, BHLHE40 has a very similar effects in Notch signaling in cancer, which induced aggressive regeneration of tumors in thyroid cancer models." (PMID 32577154, 2020). "Significantly, BHLHE40 was observed in both well-differentiated and undifferentiated thyroid cancer, indicating that is unlikely to have a role in the differentiation status of the tumor." (PMID 32577154, 2020). "In a retrospective cohort of 54 thyroid cancers, the large majority of malignant lesions (92.5%) displayed a strong expression of BHLHE40 specifically in tumor cells, while normal adjacent thyroid tissue did not express BHLHE40." (PMID 32577154, 2020).
Arthritis (1 paper, 2021). Inflammation of a joint. "Structured literature searching of PubMed and Google Scholar databases identified Bhlhe40, Col4a2 and Pitx1 as the top-ranked candidate genes with publications related to arthritis or skeletal cell biology." (PMID 33473114, 2021).
atrial fibrillation (1 paper, 2022). A disorder characterized by an electrocardiographic finding of a supraventricular arrhythmia characterized by the replacement of consistent P waves by rapid oscillations or fibrillatory waves that vary in size, shape and timing and are accompanied by an irregular ventricular response. "Functionally, atrial enlargement, susceptibility to atrial fibrillation, atrial fibrosis, atrial electrical remodeling, and atrial inflammation were found in the WT mice of Ang II infusion, whereas the loss of Bhlhe40 significantly attenuated Ang II-induced five-index changes." (PMID 36304536, 2022).
autoimmune encephalitis (1 paper, 2016). Inflammation of the brain secondary to an immune response triggered by the body itself. "Indeed, one of the differentially expressed transcription factors in our dataset, Bhlhe40, was recently shown to drive GM-CSF expression in a fraction of Th1 and Th17 cells during experimental autoimmune encephalitis." (PMID 27923070, 2016).
autosomal dominant congenital cataracts (1 paper, 2021). "PANK4 has been linked to autosomal dominant congenital cataracts and BHLHE40 is a transcriptional repressor also involved in NOTCH signaling." (PMID 34215186, 2021).
bone resorption disease (1 paper, 2022). A disease that has its basis in the disruption of bone resorption. "Our research reveals a novel Bhlhe40/Fos/Nfatc1 axis involved in osteoclastogenesis and may provide a theoretical basis and potential targets for the development of novel strategies for bone resorption diseases." (PMID 35619122, 2022).
Cerebral ischemia (1 paper, 2024). Restriction of arterial blood supply to the brain associated with insufficient oxygenation to support the metabolic requirements of the tissue. "Similarly, BHLHE40 was reported to be downregulated during cerebral ischemia, and its overexpression was shown to be protective." (PMID 39471208, 2024).
Chlamydia infection (1 paper, 2024). "The T cell-intrinsic requirement of Bhlhe40 prompted us to identify the essential CD4 T cell effector functions controlled by Bhlhe40 during Chlamydia infection." (PMID 38271477, 2024).
colorectal adenocarcinoma (1 paper, 2023). The most common type of colorectal carcinoma. "In further support of this notion, BHLHE40 mRNA levels are positively correlated with ETV1, JMJD1A and JMJD2A in the 592 colorectal adenocarcinomas represented in The Cancer Genome Atlas (TCGA)." (PMID 36890812, 2023).
Crohn disease (1 paper, 2025). A gastrointestinal disorder characterized by chronic inflammation involving all layers of the intestinal wall, noncaseating granulomas affecting the intestinal wall and regional lymph nodes, and transmural fibrosis. "Multiple omics analyses identified RUNX2 and BHLHE40 as key factors driving TRM characteristic of Crohn’s disease." (PMID 40906156, 2025).
esophageal cancer (1 paper, 2020). A primary or metastatic malignant neoplasm involving the esophagus. "On the other hand, a study using esophageal cancer cell lines showed that BHLHE40 overexpression promoted apoptosis as indicated by an increase in PARP cleavage." (PMID 32577154, 2020).
heart arrhythmia (1 paper, 2019). "Five genes (PRKCG, EREG, BHLHE40, KLF10, and NAMPT) targeted by AA-miRNAs may contribute to the pathogenesis of heart arrhythmia such as AF." (PMID 31607954, 2019).
heart failure (1 paper, 2022). Inability of the heart to pump blood at an adequate rate to meet tissue metabolic requirements. "This is the first study to suggest that Bhlhe40 is a novel regulator of AF progression, and identifying Bhlhe40 may be a new therapeutic target for hypertrophic remodeling and heart failure." (PMID 36304536, 2022).
Hypercholesterolemia (1 paper, 2025). An increased concentration of cholesterol in the blood. "We also wish to note that the knockdown experiment with Pcsk9 and Bhlhe40 in SNP-bearing atherogenic mice blunted but did not completely remove the SNP effect on hypercholesterolemia and plaques." (PMID 40591411, 2025).
influenza (1 paper, 2024). An acute viral infection of the respiratory tract, occurring in isolated cases, in epidemics, or in pandemics; it is caused by serologically different strains of viruses (influenzaviruses) designated A, B, and C, has a 3-day incubation period, and usually lasts for 3 to 10 days. "Previous studies have established a role for Bhlhe40 in host resistance to several intracellular pathogens including M. tuberculosis, T. gondii, and influenza." (PMID 38271477, 2024).
invasive ductal carcinomas (1 paper, 2020). "Another study of 147 patients with invasive breast ductal carcinomas showed that BHLHE40 expression was elevated in invasive ductal carcinomas and positively correlated with tumor grade (P = 0.023)." (PMID 32577154, 2020). "A fourth study of 1080 patients with primary invasive ductal carcinoma showed that BHLHE40 expression increased from normal to benign to premalignant and plateaued from premalignant to malignant phenotype." (PMID 32577154, 2020).
juvenile arthritis (1 paper, 2023). "Proinflammatory CD4+ cells with a similar BHLHE40+ phenotype have been identified in the joints of patients with juvenile arthritis and these cells expressed GM-CSF, TNF-α, and IFN-γ." (PMID 37751304, 2023).
lipid metabolism disorders (1 paper, 2024). "BHLHE40 was found to promote obesity through various pathways, while PPP1CB and CSNK1E counteracted lipid metabolism disorders, and modulated cytokines, immune receptors, T cells, and monocytes." (PMID 39351493, 2024).
liver fibrosis (1 paper, 2025). "Specifically, THBS1 stands out as a particularly significant gene in this network, with its regulation by both SMC3 and BHLHE40 highlighting its central role in the progression of liver fibrosis and T2DM." (PMID 40299397, 2025).
lupus (1 paper, 2024). "However, a much larger set of TFs contained in the TNF-α signaling gene set appeared among the active TFs in lupus cells; these include FOSL1, KLF6, RELB, BHLHE40, EGR3, and SMAD3." (PMID 39688922, 2024).
lymph node metastasis (1 paper, 2023). "In univariate and multivariate analyses, lymph node metastasis, N stage, BHLHE40 expression, and AJCC stage were independently associated with poor prognosis." (PMID 37377917, 2023). "Furthermore, we found that the overexpression of BHLHE40 was significantly associated with T stage, lymph node metastasis, and American Joint Committee on Cancer (AJCC) stage in a cohort of 61 PDAC patients." (PMID 37377917, 2023). "BHLHE40 expression was positively correlated with lymph node metastasis, T stage, and American Joint Committee on Cancer (AJCC) stage." (PMID 37377917, 2023). "Clinical sample analysis further validated the important role of BHLHE40 in the prognosis and progression of PDAC, and BHLHE40 was positively correlated with lymph node metastasis, T stage, and AJCC stage and negatively correlated with survival time." (PMID 37377917, 2023).
major depressive disorder (1 paper, 2015). An episode of depression lasting two or more weeks without an intervening episode of mania. "Intriguingly, Bhlhe40, Dbp and Nr1d2 are among the top-ranked genes that are rhythmically expressed in the human brain, and individuals with major depressive disorder appear to have lost the alignment between Bhlhe40 and Per2 expression timetables in six brain regions, e.g. in the amygdala." (PMID 25820768, 2015).